RNU1-36P (RNA, U1 small nuclear 36, pseudogene)
Gene: Small nuclear RNA gene on chromosome 4 (88,000,237 to 88,000,401, forward strand). Ensembl gene ENSG00000202000.
Homologues: Orthologues: chimpanzee U1 (94% identical), macaque U1 (89% identical). Paralogues in human: RNU1-89P (82% identical), RNU1-1 (80% identical), RNU1-2 (80% identical), RNU1-27P (80% identical), RNU1-28P (80% identical), RNU1-3 (80% identical), RNU1-4 (80% identical), RNVU1-18 (80% identical), RNVU1-29 (80% identical), U1 (80% identical), RNU1-19P (79% identical), RNVU1-28 (79% identical), and 134 more.